GCG (glucagon)
Diseases named in the same sentence as GCG in open-access papers (continued):
Sharing a sentence is not in itself a finding about the gene and the disease.
diabetes (continued). "In elderly patients with diabetes, studies have found that chronically reduced insulin secretion, low insulin concentrations, or high glucagon levels can lead to impaired insulin signaling in the brain." (PMID 35833084, 2022). "This apparent uncoupling of Stmn2 and glucagon suggests that Stmn2 is required for the trafficking of glucagon to Lamp2+ lysosomes in the normal regulation of glucagon secretion, and that, in diabetes, this step is impaired." (PMID 34923907, 2022). "As glucagon signaling plays a central role in glucose homeostasis and contributes to diabetes pathophysiology, there has been considerable interest in targeting the GCGR for treatment of diabetes." (PMID 36334626, 2022). "At 24 h after the induction of diabetes, the number of glucagon-positive cells has significantly increased." (PMID 35563364, 2022). "As part of a series of experiments to measure the effect of diabetes‐associated genetic variation in TCF7L2 on islet cell function, hepatic vein insulin and glucagon concentrations were measured at 2‐minute intervals during fasting and a hyperglycemic clamp." (PMID 35822422, 2022). "In this review, we provide a clear overview of various theories of hormonal regulation of diabetes, with a focus on the essential roles of glucagon and its specific receptor in the pathogenesis of diabetes." (PMID 35784565, 2022). "In order to further determine the role of lysosomal trafficking of glucagon in diabetes, we cultured αTC1-6 cells in media containing 16.7 mM glucose to induce a diabetic phenotype of glucagon hypersecretion." (PMID 34923907, 2022). "To mimic hyperglucagonemia in diabetes, we established in vitro and in vivo models using high doses of glucagon (100 nM for primary hepatocytes and 2 mg/kg for mice)." (PMID 35046401, 2022). "It was shown that glucagon secretion significantly decreased when oral BME administration on HFD/streptozotocin (STZ)-induced diabetes in mice." (PMID 37009042, 2022). "Even more recently, researchers have investigated a novel somatostatin receptor-2 antagonist, ZT-01, which they have used to stimulate glucagon release in rats with diabetes." (PMID 36992764, 2022). "VDBP can regulate the α-cell phenotype, leading to smaller and hyperplastic α cells, more F-actin microfilaments, changes in Na+-channel conductance, α-cell activation impairment, and decreased glucagon secretion, which further affects diabetes pathogenesis." (PMID 36014788, 2022). "The effectiveness of these drugs on diabetes and obesity is primarily due to the regulation of glycemia, insulin, and glucagon secretion." (PMID 35054924, 2022). "The hyperglycemic actin of aberrantly secreted glucagon is recognized as an important mechanism for the pathogenesis of diabetes." (PMID 36394315, 2022). "Nonetheless, the promotion of glucose‐dependent insulin secretion, coupled with reduced glucagon release, represents an ideal paradigm for diabetes therapy." (PMID 33822370, 2022). "Since diabetes is a bihormonal disease that not only impaired insulin action but also elevated glucagon resulting in diabetic complication, the study reported that dysregulation of glucagon secretion has also been involved in the pathophysiology of T2DM." (PMID 35211170, 2022). "Specific deletion of islet β cell cilia not only impairs insulin secretion, but also affects glucagon and somatostatin secretion of proximal α and δ cells, leading to diabetes." (PMID 36552853, 2022). "The GQD and metformin groups represented similar insulin and glucagon co-expression pattern as the diabetes group." (PMID 35858880, 2022). "One, eight and 15 months into diabetes witness significant changes in the pattern of distribution of both glucagon and nNOS." (PMID 35563364, 2022). "There were no statistical differences regarding initial presentation, including, age, diabetes ketoacidosis, the number of positive diabetes antibodies, body mass index, HbA1c, fasting c-peptide or glucagon." (PMID 36566274, 2022).
diabetes (continued). "Accumulating data suggest that diabetes is a “bi-hormonal” disease characterized by relative hypoinsulinemia and hyperglucagonemia, and the increased glucagon aggravates hyperglycemia by activating hepatic glucose production." (PMID 36334626, 2022). "Further studies were conducted in αTC1-6 cells cultured in media containing high glucose (16.7 mM) for 2 weeks to mimic glucagon hypersecretion of diabetes." (PMID 34923907, 2022). "Dasiglucagon (ZegalogueTM), a ready-to-use 29 aa linear peptide analog of glucagon, is used for the treatment of severe hypoglycemia in diabetes patients." (PMID 35164339, 2022). "Based on text mining, most of the highly common diabetes-related genes in the literature were correlated with glucagon and AMPK signaling pathways such as HNF4A, PCK2, and SIRT1, which were among the most interactive genes in the PPI analysis." (PMID 36360783, 2022). "It has been well established that abnormal elevation in circulating glucagon leads to an increase in hepatic glucose production and glycogen metabolism that contribute to hyperglycaemia in diabetes." (PMID 36005280, 2022). "In conclusion, our findings suggest a proof-of-concept model in which diabetes suppresses trafficking of glucagon and Stmn2 from the late endosome toward the Lamp2A+ lysosomes." (PMID 34923907, 2022). "Another important pathophysiology of diabetes is increasing glucagon secretion despite hyperglycemia." (PMID 35211170, 2022). "During last few decades, inhibition of glucagon secretion or its action to improve insulin sensitivity and decrease insulin resistance is one of numerous therapeutic approaches to treat type 2 diabetes mellitus." (PMID 36307866, 2022). "In the islet of the diabetes group, there were a few insulin positive cells randomly distributed, with some glucagon positive cells aggregated in the center." (PMID 35858880, 2022). "This study provides the first insight into β-sitosterol glucoside’s effect on insulin resistance and glucagon levels in diabetes progression." (PMID 35624887, 2022). "In contrast, STZ-induced diabetes significantly reduced levels of colocalization between glucagon and Lamp2A (PCC 0.14 ± 0.03; p < .001) and also between Stmn2 and Lamp2A (PCC 0.15 ± 0.03; p < .001)." (PMID 34923907, 2022). "More importantly, our research found that patients with Type 2 diabetes mellitus with the highest OCN levels had lowest serum glucagon at postprandial 0.5 h and 1 h." (PMID 36307866, 2022). "The patient had brittle diabetes and was found to have an elevated glucagon level of 359 ng/L (normal 0–95 ng/mL), which was concerning for the presence of a glucagonoma." (PMID 33377995, 2021). "The influence of glucagon in the pathogenesis of type 2 diabetes mellitus is now recognized, and a crucial mechanism that regulates glucagon secretion was reported nearly a decade ago." (PMID 35002748, 2021). "The primary cause of type 2 diabetes mellitus (T2DM) is insulin resistance and relative insulin deficiency; however, many subjects also exhibit inappropriate levels of circulating glucagon." (PMID 33758717, 2021). "Given the use of glucagon to rescue severe insulin-induced hypoglycaemia T1DM and its ascribed role in the hyperglycaemia of diabetes, the concept of using glucagon agonists therapeutically initially seems illogical." (PMID 34093449, 2021). "Diabetes is a metabolic syndrome rooted in impaired insulin and/or glucagon secretory responses within the pancreatic islets of Langerhans (islets)." (PMID 34045505, 2021). "This reflects increased glycogen catabolism, glucagon release and gluconeogenesis finally leading to the high prevalence of diabetes mellitus (21-37%) in PPGL patients." (PMID 34557163, 2021). "We would like to think that Unger had the correct interpretation of diabetes pathogenesis and that taking into account these cultural advances concerning glucagon, we can soon arrive at the key to understanding diabetes." (PMID 34572493, 2021).
diabetes (continued). "Even in adolescents, glucagon response to hypoglycemia is blunted within the first year of diabetes diagnosis." (PMID 34572493, 2021). "After ingesting a mixed meal, blood glucagon levels become significantly higher in people with diabetes than in healthy individuals, and the peak level is reached within 30 min after ingestion." (PMID 34199839, 2021). "Diabetes-related plasma biomarkers insulin, leptin, resistin, and glucagon were significantly reduced by quercetin supplementation." (PMID 34439499, 2021). "The pancreas maintains the plasma glucose balance by different exocrine hormones, such as insulin and glucagon, and diabetes is a disability of pancreas function." (PMID 34690937, 2021). "At the age of 7.5 months, Wfs1 KO rats showed the first signs of diabetes by reduced c-peptide and insulin, and increased glucagon secretion (p < 0.01)." (PMID 34831417, 2021). "And GLP-1 plays an important role in promoting insulin secretion, inhibiting glucagon secretion and stimulating the proliferation and differentiation of islet beta cell in patients with diabetes." (PMID 34001220, 2021). "Diabetes is the result of a cluster of metabolic alterations including insulin resistance, lower insulin secretion, or increased glucagon secretion leading to hyperglycemia." (PMID 33467677, 2021). "Inappropriate glucagon response to meal ingestion has been observed in almost all types of diabetes including T2D (type 1 diabetes, secondary diabetes to chronic pancreatitis or pancreatectomy, and maturity-onset diabetes of the young)." (PMID 34199839, 2021). "As patients with T1D lose the ability to secrete glucagon within the first few years after diabetes onset, the sympathoadrenal response becomes crucial for the physiological recovery from hypoglycaemia." (PMID 33855225, 2021). "Linagliptin is a dipeptidyl peptidase-4 inhibitor that reduces blood sugar by increasing insulin and decreasing glucagon production by the pancreas, used to treat diabetes mellitus type 2." (PMID 33525510, 2021). "Increased plasma glucagon at fasting and post glucose stimulus starts before glucose intolerance and diabetes as a consequence of insulin resistance in α-cells." (PMID 33320449, 2021). "We explore possible clues gleaned from these studies in how inhibition of glucagon secretion can be targeted as a treatment for diabetes mellitus." (PMID 34659118, 2021). "Knowledge gaps in any of these four mechanisms governing glucagon and insulin physiology will severely limit the development of diabetes models." (PMID 35002748, 2021). "In the setting of diabetes, defects in δ-cell function lead to suboptimal insulin and glucagon outputs and lift the glycemic set-point." (PMID 33494193, 2021). "After developing methods for isolating human pancreatic alpha cells, this discovery will be useful for study of behaviors such as the mechanism of glucagon secretion and the pathophysiology of hyperglucagonemia in diabetes patients." (PMID 33428669, 2021). "To further investigate the functional implication of the histological changes in the endocrine pancreas of diabetic Prlr-/- mice, we determined the pancreatic expression and circulating levels of insulin and glucagon 11 weeks after inducing diabetes with STZ." (PMID 33746901, 2021). "Unlike in healthy individuals where glucagon levels elevate under conditions of hypoglycemia, some patients with diabetes present increased blood glucagon levels despite hyperglycemia." (PMID 34319011, 2021). "Targeting dipeptidyl peptidase-IV (DPP-IV) inhibition in diabetes leads to improvement of impaired insulin secretion, reduction of glucagon, and eventually lowering of bloodstream glucose." (PMID 33670795, 2021). "The interest for the study of glucagon is also due to the reason that in patients with diabetes suffering for severe hypoglycemic events the administration of glucagon, by either injection or nasal intake, is an important therapeutic option." (PMID 33828527, 2021).
diabetes (continued). "When people with diabetes ingest a mixed meal, blood glucagon and incretin are known to reach their peak level after approximately 30 min." (PMID 34199839, 2021). "Despite the centrality of glucagon to diabetes etiology, there remains considerable uncertainty about the regulation of its release and the relative importance of intra-islet effects and systemic factors." (PMID 34787082, 2021). "Type 2 diabetes mellitus (T2DM) is a metabolic disorder of complex aetiology characterised by a deficiency, and/or dysfunction of endogenous insulin and glucagon production." (PMID 34081167, 2021). "As a glucagonostatic hormone, GLP-1 inhibits glucagon secretion, which is paradoxically increased in diabetes." (PMID 33320449, 2021). "On the other hand, Ala, a non-essential amino acid, was reported to be increased in hyperinsulinemia conditions in diabetes, and supplementation of Ala improved glucagon response to hypoglycaemia events in diabetes." (PMID 34335259, 2021). "Finding novel anti-diabetic compounds with effective suppression activities against hepatic glucagon response is urgently required for the development of new drugs against diabetes." (PMID 35211458, 2021). "For example, TPC2-/- mice show defects in cholesterol degradation, leading to hypercholesterinemia; TPC2 absence also results in mature-onset obesity, and a role in glucagon secretion and diabetes has been proposed." (PMID 33465068, 2021). "The role of glucagon in the development of diabetes is widely accepted and supported by many studies that showed its role in the regulation of body mass and energy expenditure by its central action on food intake." (PMID 32411223, 2020). "The key role of glucagon in diabetes pathogenesis has largely been described by Professor Roger Unger in his scientific production, and α-cell dysfunction and insulin unresponsiveness have been suggested and researched." (PMID 33020399, 2020). "This cultural progress clarified the roles of gastrointestinal hormones as well as pro-glucagon and α-cells in diabetes pathophysiology." (PMID 33020399, 2020). "Elevated plasma glucagon is an early symptom of diabetes, occurring in subjects with impaired glucose regulation." (PMID 32446876, 2020). "The selection of appropriate Kampo medicines for the treatment of diabetes in consideration of their effects on glucagon signaling and glucagon production will be important." (PMID 32215330, 2020). "GLP-1, which is used widely to treat diabetes and obesity, promotes glucose-induced insulin secretion, inhibits glucagon secretion and suppresses the appetite and food intake by slowing gastric emptying and increasing satiety." (PMID 32937828, 2020). "This represents an exciting – but challenging – area of future research into the dysregulation of glucagon secretion in diabetes." (PMID 32716554, 2020). "Excessive activation of this pathway in diabetes dysregulates glucagon secretion through alpha cell oxidative stress and reduced ATP synthesis." (PMID 32774668, 2020). "Both insulin and glucagon have been of significant focus, due to the key roles in glucose metabolism, diabetes and other disorders." (PMID 32296396, 2020). "A fatty liver is a main driver for a new recognized liver-pancreatic α-cell axis and increased glucagon, contributing to diabetes pathophysiology." (PMID 32684985, 2020). "The expression of PAI-1 gene in the liver seems to increase in diabetes mellitus, as well as in several protocols of hepatic injury, and is mainly attributed to mechanisms mediated by glucagon and/or reactive oxygen species." (PMID 32161725, 2020). "Of the seven patients that we identified who had potential false positive fasting plasma glucagon concentrations, three had diabetes mellitus, two had end stage renal failure and one had chronic pancreatitis." (PMID 33391185, 2020).
diabetes (continued). "Prior to this study, a diabetic mouse model fed with Enzogenol® was reported to improve diabetes-related biomarkers with a reduction in HbA1c, insulin, and glucagon levels, and an elevation of hepatic AMP-activated protein kinase (AMPK) activity." (PMID 32075228, 2020). "In diabetes, secretion of glucagon is inadequately high at high glucose, exacerbating hyperglycaemia, and inadequately low at low glucose, possibly leading to fatal hypoglycaemia." (PMID 32218947, 2020). "Cotadutide is a balanced GLP-1/glucagon dual agonist which has been shown in phase 2 trials in people with diabetes and obesity to significantly improve and to reduce body weight by 2–3 kg in comparison to placebo." (PMID 32436022, 2020). "As described in the next section, oxidative stress and mitochondrial alterations increase glucagon secretion at normal and high glucose and are therefore likely to accelerate the occurrence of frank hyperglycemia characteristic of diabetes." (PMID 32774668, 2020). "The dysregulation of glucagon secretion in T2D is detectable even prior to the onset of diabetes; hyperglucagonaemia is observed in obese patients and patients with impaired fasting glycaemia." (PMID 32446876, 2020). "Alpha cell dysfunctions such as insulin resistance, mitochondrial alterations, and oxidative stress contribute to the pathogenesis of type 2 diabetes and glucagon dysregulation in diabetes." (PMID 32774668, 2020). "It was suggested that reducing glucagon action or its secretion will lead to potent reductions in the elevated hepatic glucose production observed in both Type I and II diabetes mellitus." (PMID 32580324, 2020). "A fatty liver is a main driver for a new recognized liver-pancreatic α-cell axis and increased glucagon, putatively contributing to diabetes pathophysiology." (PMID 32684985, 2020). "Inhibition of glucagon hypersecretion from pancreatic α-cells is an appealing strategy for the treatment of diabetes." (PMID 32117057, 2020). "That is, glucagon and GRs have extremely important roles in the glucose intolerance in diabetes, and the glucagon pathway as therapeutic targets has attracted attention." (PMID 31357734, 2019). "Higher FBG level is due to increase in glucagon to insulin ratio as seen in diabetes, where liver is involved in excess glycogen breakdown and gluconeogenesis." (PMID 31080251, 2019). "During that decade, several authors showed the efficacy of IN glucagon to resolve hypoglycemia in normal volunteers and in patients with diabetes, both adults and children." (PMID 31349701, 2019). "Diabetes is characterized by hyperglycemia due to impaired insulin secretion and aberrant glucagon secretion resulting from changes in pancreatic islet cell function and/or mass." (PMID 30805033, 2019). "This usability advantage over existing GEKs will hopefully inspire more confidence in caregivers of patients with diabetes and translate to more widespread use of glucagon in treating severe hypoglycemia in the home or ambulatory setting." (PMID 31219349, 2019). "The final example presented in this work considers how glucagon response within a patient with Type 1 diabetes mellitus (T1DM) varies during periods of hypoglycemia." (PMID 31829209, 2019). "We measured medical students’ knowledge and attitudes toward diabetes, hypoglycemia, and glucagon before and after the training." (PMID 31138204, 2019). "IN glucagon drops, powders, and sprays increase blood glucose levels in healthy volunteers and in patients with diabetes, both under normal circumstances and during hypoglycemia." (PMID 31349701, 2019). "During a hypoglycemia emergency, a person with diabetes should receive a full dose of glucagon in both a timely and reliable manner." (PMID 31219349, 2019). "Diabetes is also characterised by impaired glucagon secretion in response to hypoglycaemia, which increases the risk of therapy-related glucopenia." (PMID 30953108, 2019).